TXNIP (thioredoxin interacting protein)
Diseases named in the same sentence as TXNIP in open-access papers (continued):
Sharing a sentence is not in itself a finding about the gene and the disease.
bacterial infection (3 papers, 2019 to 2024). "Another interesting idea is the development of TXNIP inhibitors, which represents a promising therapeutic strategy for enhancing immunity against pathogenic bacterial infections, increasing the antioxidant activity of Trx, and reducing apoptosis." (PMID 38790650, 2024). "Research has demonstrated that TXNIP plays a critical role in modulating the immune response during bacterial infections." (PMID 38790650, 2024). "Despite these advances, investigation into the potential of TXNIP inhibitors to enhance the immune system in the context of bacterial infections remains relatively incomplete." (PMID 38790650, 2024). "Here, we identified the critical role of thioredoxin-interacting protein (TXNIP) in the production of IFN-γ in NK cells during bacterial infection." (PMID 33327533, 2020). "Here, we investigate the function of TXNIP in the production of IFN-γ in NK cells to activate macrophages during bacterial infection in vitro and in vivo." (PMID 33327533, 2020). "Our findings suggest that NK cell-derived IFN-γ is critical for host defense and that TXNIP plays an important role as an inhibitor of NK cell-mediated macrophage activation by inhibiting the production of IFN-γ during bacterial infection." (PMID 33327533, 2020). "In conclusion, NK cell-derived IFN-γ production is crucial for macrophage activation, and TXNIP plays a critical role in the production of IFN-γ in NK cells during bacterial infection." (PMID 33327533, 2020). "In the same manner, differential TXNIP expression levels are thought to be important in regulating cellular or tissue homeostasis during bacterial infection." (PMID 31781121, 2019). "Emerging as a potentially more effective strategy is the utilization of immunomodulatory peptides or TXNIP inhibitors, which could bolster the host’s innate defenses against bacterial infections." (PMID 38790650, 2024). "We assessed whether TXNIP could regulate the activity of NLPR3 inflammasomes following bacterial infection." (PMID 31781121, 2019). "The multifunctional nature of TXNIP and its central role in disease pathogenesis suggests that inhibiting this protein could offer novel therapeutic avenues not only for these conditions but also for modulating the immune response to bacterial infections." (PMID 38790650, 2024). "However, whether TXNIP can regulate other functions of NK cells, including cytotoxicity and/or cytokine production, especially under PAMP stimulation or bacterial infection, has not been thoroughly investigated." (PMID 33327533, 2020).
heart disease (3 papers, 2015 to 2020). "Elevated levels of PDK4 and thioredoxin interacting protein (TXNIP), and decreased expression of the array of genes associated with both heart diseases and compromised glucose metabolism were observed." (PMID 32804947, 2020).
hematological malignancies (3 papers, 2020 to 2021). "TXNIP has been identified as potential tumor suppressor gene in various solid tumors and hematological malignancies." (PMID 32013265, 2020). "Phenotypically, mutant ASXL1 impairs the BAP1-ASXL1-FOXK1/K2 transcriptional nexus and downregulates TXNIP, VHL, and SOCS1/2, and consequently promotes glucose metabolism and enhances oncogenic HIF-1α and JAK-STAT3 signaling pathways known to be altered in hematological malignancies." (PMID 32683582, 2021).
retinopathy (2 papers, 2024). "HE staining and the retinal vascular analysis revealed that ACT improved retinopathy, but pc-TXNIP and LY294002 reversed these improvements." (PMID 39689088, 2024).
central nervous system disorder (1 paper, 2025). A disease involving the central nervous system. "It has been reported that pathological neuroinflammation were associated with TXNIP in some central nervous system disorders, especially via the TXNIP/NLRP3 pathway." (PMID 40388874, 2025).
infectious disease (1 paper, 2024). A disorder directly resulting from the presence and activity of a microbial, viral, or parasitic agent in humans. "Identifying and developing effective TXNIP inhibitors for this purpose would not only broaden the understanding of TXNIP’s role in immunity but also potentially lead to innovative treatments for infectious diseases." (PMID 38790650, 2024).
inherited metabolic disorder (1 paper, 2025). "Our data, together with a previous report on three siblings from a single consanguineous family who were homozygous for another TXNIP loss-of-function variant (c.174_175delinsTT), support TXNIP deficiency as a novel inherited metabolic disorder." (PMID 41116060, 2025).
liver (1 paper, 2022). "RAPA eliminates excessive ROS, inhibits NF-κB nuclear translocation and down-regulates the TXNIP/NLRP3 axis, consequently suppressing ROS-mediated NLRP3 inflammasome activation, which may be the underlying mechanism of the protective effect of autophagy on realgar-induced liver injury." (PMID 35628508, 2022).
peripheral neuropathy (1 paper, 2022). A disorder affecting the peripheral nervous system. "The pathogenesis of peripheral neuropathy in T2DM rats may be linked to TXNIP/NLRP3 inflammasome pathway activation, indicating the potential of this pathway as a therapeutic target for diabetic peripheral neuropathy (DPN)." (PMID 35845136, 2022).
psychiatric disorder (1 paper, 2022). A disorder characterized by behavioral and/or psychological abnormalities, often accompanied by physical symptoms. "Considering the critical roles of TXNIP in linking oxidative stress and inflammation, our limited knowledge about its involvement in the central nervous system (CNS) makes it necessary further to investigate its function in healthy brain and psychiatric disorders." (PMID 36291328, 2022). "By involving healthy and diseased brain samples, and animal and clinical cohort, our study provides further insight into the function of TXNIP in CNS and their roles in psychiatric disorders, which could facilitate its involvement in drug development for brain therapy." (PMID 36291328, 2022).
TXNIP also shares sentences with these, for which no sentence is quoted: cerebrovascular diseases (3 papers); gestational diabetes (3); Hyperinsulinemia (3); ischemia reperfusion injury (3); acute coronary syndrome (2); acute myocardial infarction (2); adenocarcinoma (2); angina (2); autoimmune disease (2); brain cancer (2); cognitive decline (2); endometriosis (2); glucose metabolism disorder (2); hyperhomocysteinemia (2); ischemic cardiomyopathy (2); preeclampsia (2); abnormal glucose tolerance (1); acute liver failure (1); adult T-cell leukemia (1); alcoholic fatty liver disease (1); alcoholic hepatitis (1); alopecia (1); amyloid (1); anaplastic thyroid cancers (1); animal disease (1); aortic stenosis (1); aplastic anemia (1); Arrhythmia (1); arteriosclerosis (1); benign oncocytomas (1).
A further 51 diseases each share a sentence with TXNIP in 1 paper.